PSMB8 (proteasome 20S subunit beta 8)
Diseases named in the same sentence as PSMB8 in open-access papers (continued):
Sharing a sentence is not in itself a finding about the gene and the disease.
tumor (continued). "Taken together, upregulation of miR-451a inhibited cell proliferation and induced apoptosis in NOZ and TGBC2TKB cells, partly through regulation of MIF, PSMB8 and CDKN2D, suggesting that miR-451a has a tumor-suppressing role and could be a novel therapeutic target in GBC cells." (PMID 34112884, 2021). "However, the observation that high expression of PSMB8 correlated with lower overall survival does not hold for all types of neoplasms." (PMID 34944095, 2021). "In the analysis of gene expression in whole proteasomes including PSMB5 (β5), PSMB8 (iβ5), PSMB7 (β2), PSMB10 (iβ2), PSMB6 (β1), and PSMB9 (iβ1), these genes alternated or showed only slight in their expression following silencing of PSMB5 or PSMB7 in three tumor cells." (PMID 29515784, 2018). "Although we did not analyze the overall level of protein expression in our cohort, it is possible that the number of cells expressing PSMB8 or PSMB9, but not the overall level of expression throughout the sample, increases with tumor grade." (PMID 36746983, 2023). "Similarly, the expression of TAP2, TAPBP, PSMB8, and B2M was each shown to be induced by VC treatment in the WT, but not TET2-KO, tumor cells." (PMID 39388288, 2024).
cancer (69 papers, 2009 to 2025). A tumor composed of atypical neoplastic, often pleomorphic cells that invade other tissues. "As such, PSMB8 is a key driver of oncogenesis in many cancers, including colitis-induced cancers, which are associated with chronic inflammatory conditions." (PMID 40698074, 2025). "More broadly, a pan-cancer analysis found that of 33 cancer types assessed, overexpression of PSMB8 in certain cancers was associated with poor clinical outcomes." (PMID 41228214, 2025). "PSMB8 is one of the immune subunits (β5i) of the immunoproteasome; it has a chymotrypsin-like activity and its elevated expression in different cancers has been associated with poor disease outcome." (PMID 41228214, 2025). "Recent studies in various cancer types have shown that overexpression of IP subunits (PSMB8, PSMB9, PSMB10) is associated with improved survival and better response to ICI therapies." (PMID 41222746, 2025). "The downregulated genes of Co.sh vs sh-M#2 were associated with multicellular organismal processes, responses to endogenous stimuli, and cell adhesion, suggesting that PSMB8 was closely associated with cellular biological processes and migration in cancer." (PMID 40335825, 2025). "Although overexpression of the PSM genes was most frequently associated with prognosis, underexpression of PSMB8-10 had a major impact on prognosis in several cancer types." (PMID 36123629, 2022). "In brief, DCs were the most closely-associated with PSMB8 levels in the scope of pan-cancer, and both were observed to correlate with the antigen-presenting system." (PMID 34650125, 2021). "Recent studies have implicated PSMB8 in cancer progression, where it acts as a regulatory molecule." (PMID 40334200, 2025). "Psmb8 (proteasome subunit beta type-8) encodes the catalytic immunoproteasome subunit, has been linked to various cancers, and could be targeted by the selective alpha1a adrenoreceptor antagonist Fiduxosin, according to in silico studies." (PMID 39595046, 2024). "Targeting NLRC5 promoter demethylation through TRED-I system can upregulate MHC-I, B2M, TAP1 and genes encoding immune proteasome components (LMP2/PSMB9/β1i, LMP7/PSMB8/β5i), thereby enhancing CD8+T cell-mediated anti-cancer immunity." (PMID 40191187, 2025). "iii) There was a strong and statistically significant correlation between the expression level of the immunoproteasome subunit β5i (PSMB8) and the response to carfilzomib among the cancer cell lines tested." (PMID 41339338, 2025). "Given that the amounts of PSMB8- and PSMB9-expressing cells increase with grades, but correlate with prolonged RFS in TNBC, we next wanted to determine if amongst higher-grade cancers, the benefits of PSMB8/9 expression are even greater." (PMID 36746983, 2023). "Lower PSMB1/2/3/7/8 proteins expressions were observed in normal glomeruli compared with cancer tissues, and lower PSMB8/10 proteins levels were observed in normal tubules compared with cancer tissues." (PMID 35693739, 2022). "At present, many studies show that abnormal expression of PSMB8 correlates with multiple cancers, including BC." (PMID 35223499, 2022). "In NSCLC patients, high expression of PSMB8 was frequently observed in cancers with more favorable outcomes." (PMID 34944095, 2021). "This study sheds light on the potential role of PSMB8 as a prognostic-indicator in different cancers." (PMID 34650125, 2021). "On the other hand, Psmb3, Psmb6, and Psmb8 are the members of the proteasome subunit and have been found in most cancers." (PMID 33919822, 2021). "To date, the mechanisms that underline the tumorigenesis capacity of PSMB8 are not fully understood, and the immunological and prognostic roles of PSMB8 in the pan-cancer background remain to be elucidated." (PMID 34650125, 2021). "Psmb8 was shown to be significantly up regulated in cancers such as bladder, breast, kidney, lung, uterine, and head and neck." (PMID 28201999, 2017).
cancer (continued). "Additionally, PCR results reveal that PSME2 and PSMB8 are highly expressed in cancer tissues, while BMP5 and BCL2 are more highly expressed in normal tissues." (PMID 41403941, 2025). "PSMB8, PSMB9 and PSMB10 are part of the immunoproteasome complex, which is activated in response to interferon gamma signaling, and has been previously associated to cancer cell survival and progression." (PMID 38519482, 2024). "Additionally, the upregulation of PSMB8 in cancer appeared to occur through a cell-intrinsic mechanism, being more prevalent in the AML–M5 subtype, which frequently harbors myeloid/lymphoid or mixed-lineage leukemia (MLL) fusions." (PMID 39335660, 2024). "As such, many studies have focused on the relationship between PSMB8 and human cancers." (PMID 35933405, 2022). "Furthermore, PSMB8-10 (PSM class I) expression was also strongly correlated with PSME1-2 (PSM class III) in 27 cancer types, e.g. BRCA." (PMID 36123629, 2022). "We hypothesized that PSMB8 hypermethylation may result in abnormal expression of PSMB8, which can affect the processing of class I MHC peptides and antigen processing and cause cancers." (PMID 35223499, 2022). "Previous studies have revealed the context-specific role of PSMB8, which varies in diverse cancers." (PMID 34650125, 2021). "A significant correlation between PSMB8 and four methyltransferase expression levels could be observed in most cancer types." (PMID 34650125, 2021). "A few papers describe the expression of PSMB8 (LMP7 gene), PA28γ activator, Rpt4 subunit of 19S activator and possible clinical significance of these components of proteasome system in patient intestine cancers." (PMID 33807574, 2021). "Nevertheless, PSMB8 (proteasome subunit beta 8), more familiar in the field of immunology contributing to the process of antigen presentation, is indeterminate in the role as a survival predictor of human pan-cancer." (PMID 34650125, 2021). "We extracted the expression of PSMB8 and visually rendered the comparison in the pan-cancer." (PMID 34650125, 2021). "Thus, correlations between PSMB8 expression and StromalScore, ImmuneScore, and ESTIMATEScore were determined in 20, 31, and 29 cancer types, respectively." (PMID 34650125, 2021). "In addition, DNA mismatch repair gene expressions were almost inversely correlated with the PSMB8 expression in pan-cancer, whereas MLH1 was of positive correlation." (PMID 34650125, 2021). "When the cancer cells were treated with 5-AC, 5/8 showed a significant upregulation of PSMB8." (PMID 28622390, 2017). "Consequently, PSMB8, as a core subunit of the immunoproteasome, may be upregulated by cancer cells to counterbalance the accumulation of misfolded or damaged proteins produced by both cellular and immune microenvironment stresses." (PMID 40334200, 2025). "Importantly, we inferred that the favorable prognosis of THCA patients with higher PSMB8 expression might result from enhanced antigen presentation and cytotoxic cell-induced apoptosis of cancer cells." (PMID 40334200, 2025). "Therefore, we sought to use these to better understand whether cancer cell heterogeneity could impact FAK function with respect to regulation of Psmb8 and MHC-I." (PMID 36977556, 2023). "Additionally, other PSM genes have been associated with cancer progression (e.g. PSMD9 (p27) and PSMD10 (p28)), increased radiation sensitivity in breast cancer (e.g. absence of p27), as well as, increased risk of colorectal cancer (e.g. PSMB8 and PSMB9)." (PMID 36123629, 2022). "Our analysis revealed that PSMB8 could regulate epigenetic status in pan-cancer." (PMID 34650125, 2021). "Specifically, TAP1, TAP2, TAPBP, PSMB8, and CALR were significantly upregulated in 17, 14, 13, 15, and 15 distinct cancer types, respectively." (PMID 38297270, 2024). "PSMB8 and PSMB9 are the most universally correlatedgenes across different cancer types, suggesting highly coordinatedproteasome activity with the HLA-I level." (PMID 37857377, 2023).
cancer (continued). "Hence, our study which investigated the general applicability of the antigen-presentation regulator PSMB8 as a prognostic biomarker in pan-cancer from an immuno-oncological perspective, could provide a rational and theoretical foundation for future mechanism studies." (PMID 34650125, 2021). "In comparison to other cancer types, STS showed high expression of PSMB5, PSMB6 and PSMB7, the subunits of the constitutive proteasome and low levels of PSMB8, PSMB9 and PSMB10, the subunits specific to immunoproteasomes." (PMID 32851475, 2021). "We further evaluated the strength of the relationship between PSMB8 expression and the TMB or MSI in pan-cancer." (PMID 34650125, 2021). "In our ESTIMATE algorithm-based analysis, all cancers types except for READ, CHOL, UVM, THYM, ESCA, GBM, and DLBC, presented a significant correlation between PSMB8 expression and DC." (PMID 34650125, 2021). "In this study, we first demonstrated the relationship among PSMB8, PSMB9, PSMB10, PSME1, PSME2, and IRF1 in the immune micro-environment and immune score through TCGA whole cancer cohorts, and further, we proved the correlation between PSMB8, PSMB9, PSMB10, PSME1, PSME2, IRF1, and immune cells." (PMID 36700205, 2022). "Interestingly, PSMB8-10 and PSME1-2 genes had a significant impact on OS in most cancer types, primarily when underexpressed." (PMID 36123629, 2022). "Besides that, other CSV interactions also can be a predictive biomarker in other cancers, such as BRWD3 and PSMB8 in LUAD (P = 8E−04, log-rank test), as well as CNTN2 and HDAC11 (P = 0.01, log-rank test) in LUAD." (PMID 36180906, 2022). "A bioinformatic study conducted across seven cancer types found that gene modules representing MHC class I function are highly expressed, and that within these modules, the most up-regulated proteasome subunits are PSMB8 and PSMB943." (PMID 28051153, 2017). "Based on transcriptomic analyses of thousands of samples from The Cancer Genome Atlas, we report that expression of constitutive proteasome (CP) genes (PSMB5, PSMB6, PSMB7) and immunoproteasome (IP) genes (PSMB8, PSMB9, PSMB10) is increased in most cancer types." (PMID 27659694, 2016). "We also identified the top 1 GEAR in individual cancer types, such as TLL1 (BLCA), PGK1 (BRCA), RFXANK (CESC), DPP7 (COAD), VWA8 (KIRC), SCMH1 (LGG), HILPDA (LIHC), TLE1 (LUAD), CD151 (LUSC), ANKRD13A (OV), SOCS2 (PAAD), DRG2 (PRAD), ADAMTS6 (STAD), PSMB8 (THCA), ASS1 (UCEC)." (PMID 41404730, 2025). "However, high-quality studies systematically elucidating the role of PSMB8 in a specific cancer type are still lacking." (PMID 40334200, 2025). "Furthermore, co-amplification of PSM genes located in close proximity to one another (e.g. PSMB5 and PSMB11, 14q11.2; PSMB4 and PSMD4, 1q21.3; PSMB8 and PSMB9, 6p21.32) or known cancer drivers (e.g. co-amplification of ERBB2 and PSMB3) were also frequently amplified together." (PMID 36123629, 2022). "In conclusion, the comprehensive pan-cancer analysis presented here demonstrated that several PSM genes (e.g. PSMA1, PSMB4-5, PSMB8-10, PSMD2, PSMD4, PSMD11, PSME1-3, and PSMG3) may be putative biomarkers for determining prognosis and choice of treatment for different cancer types." (PMID 36123629, 2022). "We boldly speculate that PSMB8 alone could not make sense to the prognosis of immunologically-inert metastases and the other cancer types likewise." (PMID 34650125, 2021). "However, the role of PSMB8, a component of the 20S proteolytic core particle of the proteasome, has not been reported in cancer." (PMID 26894977, 2016). "Despite being essential in cellular and immunological functions, the role of PSMB8 and PSMB9 has not been determined in all types of cancers, as highlighted in at least 78 publications, including 19 meta-analyses." (PMID 36937130, 2023).
infection (41 papers, 2007 to 2025). The state of being infected such as from the introduction of a foreign agent such as serum, vaccine, antigenic substance or organism. "Our results show comparable induction of PSMB8, 9 and 10 upon stimulation with CM and direct infection." (PMID 40872920, 2025). "In contrast, compared with Ad-GFP infection, Ad-Psmb8-mediated overexpression of Psmb8 reduced Drp1 ubiquitination and protein levels." (PMID 39516219, 2024). "The PSMB8 locus encodes low molecular mass polypeptide 7 (LMP7) of the immunoproteasome, which is involved in antigen processing and presentation during infection." (PMID 32792854, 2020). "Compared with Ad-GFP infection, Ad-Psmb8 infection increased Psmb8 protein levels by approximately 1.5-fold and dramatically suppressed the H/R-induced increases in the percentage of apoptotic cardiomyocytes (TUNEL assay) and mitochondrial division (MitoTracker red staining)." (PMID 39516219, 2024). "The results indicated that siRNA-Psmb8 infection markedly prolonged the half-life of the Drp1 protein compared with that in cells infected with siRNA-control; however, compared with Ad-GFP infection, Ad-Psmb8 infection reduced the half-life of the Drp1 protein." (PMID 39516219, 2024). "In response to inflammation or infection, proteolytic subunits of constitutive proteasome are replaced by immunoproteasome subunits Psmb8, Psmb9 and Psmb10 that are more efficient in processing endocytosed antigens for subsequent MHC I-restricted cross-presentation." (PMID 36993973, 2023). "Similarly, expression of several genes in the canonical IFN signaling pathway, including Ifng, Jak2, Stat1, Stat2, Socs1, Irf1, Irf9, Tap1, Ifitm1, Psmb8, Ifi35, Gas1 and Fit3 were up-regulated during infection by the mutant strain." (PMID 25201772, 2014). "In line with IFNs being required for ImP induction, PSMB8 and 9 were not induced by wtVSV infection, and while the signal for PSMB10 was slightly increased by wtVSV, the expression remained lower compared to oVSV." (PMID 40872920, 2025). "We observed a large increase in both immunoproteasomal subunits PSMB8 and PSMB10, and the IFN-activated proteins ISG15 and MX1 in serum and in infected cells 3 and 7 days after infection, thus connecting these changes in blood proteins to those after SARS-CoV-2 infection." (PMID 37739942, 2023). "PSMB8 overexpression reduces the virus-induced activation of NF-κB promoters and suppresses the expression of proinflammatory IL-1β, TNF-α, IL6, IL8, and IFN-γ upon infection with nerve necrosis virus." (PMID 38031182, 2023). "However, in response to infection, male mice exhibited higher expression levels of CXCL2 (KO, 1A3, and 6A2), SAMHD1 (1A0, 1A3), RSAD2, STAT1, and STAT3 (1A0), MYD88 and PSMB8 (1A3), BCL3, BCL10, CCRL2, IFITM2, RTP4, and ZFP36L1 (6A2), compared to females." (PMID 32670284, 2020). "We then silenced each of the top four upregulated PSMBs (PSMB1, PSMB4, PSMB8 and PSMB9, fold change >1.5) using shRNA in HEK293T cells and examined the viral replication in PSMB-silenced cells after VSV-expressing GFP (VSV-GFP) infection." (PMID 30682859, 2019). "Thus, we silenced PSMB8 in LN229 and U87 MG GBM cell lines via lentiviral infection." (PMID 40335825, 2025). "tularensis LVS-infection; a significant upregulation of genes involved in RAS pathway including Ccl2, Nfkb, p38 Mapk, Ras, Stat1, Stat3 and Tnf-α; and an upregulated expression of IFN-γ pathway genes such as Bak, Bax, Ifit, Ifn-γ, Irf, Isg, Oas1, Psmb8, Ptpn2, Stat and Tap1." (PMID 37266014, 2023). "HiRIEF LC-MS/MS detected alterations in the remaining proteins, i.e., ISG20, PSMB8, PSMB10, ALDOC, and SERPINB1, emphasising the method’s ability to capture alterations deriving from infection that are not picked up by other methods." (PMID 37739942, 2023). "Whether and how the simultaneous absence of the inducible catalytic subunits β1i/LMP2 (Psmb8), β2i/MECL-1 (Psmb9) and β5i/LMP7 (Psmb10) alters the course of infections remains unclarified." (PMID 33968021, 2021).
inflammatory myopathies (2 papers, 2014 to 2025). "In all patients with inflammatory myopathies (IM) including PM, DM and OM, immunoproteasomal subunits PSMB8 and PSMB9 were significantly increased when compared to NIM patients." (PMID 25098831, 2014). "Expression of constitutive (PSMB5, -6, -7) and corresponding immunoproteasomal subunits (PSMB8, -9, -10) was analyzed by real-time RT-PCR in muscle biopsies and sorted peripheral blood cells of patients with IIM, non-inflammatory myopathies (NIM) and healthy donors (HD)." (PMID 25098831, 2014).
ischaemic heart disease (1 paper, 2024). "Psmb8, as one of the immunoproteasome catalytic subunits, is a key regulator of protein homoeostasis, inflammation and some cardiac diseases." (PMID 39516219, 2024). "Taken together, these findings provide new insights into the mechanism by which Psmb8 regulates Drp1 stability and subsequent cardiac I/R injury and suggest that activating Psmb8 may be a promising therapeutic strategy for ischaemic heart disease." (PMID 39516219, 2024). "Our study identified a new cardioprotective role of Psmb8 in cardiac I/R damage through targeting Drp1, and highlight that increasing Psmb8 activity may constitute a promising therapy for ischaemic heart disease." (PMID 39516219, 2024).
PSMB8 also shares sentences with these, for which no sentence is quoted: cervical carcinoma (7 papers); atherosclerosis (5); experimental autoimmune encephalomyelitis (5); Alzheimer disease (4); Anxiety (4); atrial fibrillation (4); diabetes (4); epilepsy (4); multiple sclerosis (4); myocarditis (4); acute myeloid leukemia (3); adenocarcinoma (3); cardiac hypertrophy (3); Crohn disease (3); diabetic nephropathy (3); esophageal squamous cell carcinoma (3); neurological disease (3); papillary thyroid cancer (3); rheumatoid arthritis (3); triple-negative breast carcinoma (3); viral myocarditis (3); acute pancreatitis (2); cardiovascular diseases (2); Cognitive impairment (2); colorectal (2); dermatomyositis (2); emphysema (2); esophageal cancer (2); Graves disease (2); Hashimoto thyroiditis (2).
A further 116 diseases each share a sentence with PSMB8 in 2 papers or fewer.